RNU4-29P (RNA, U4 small nuclear 29, pseudogene)
Gene: Small nuclear RNA gene on chromosome 9 (83,275,941 to 83,276,114, forward strand). Ensembl gene ENSG00000251752.
Homologues: Orthologues: rat LOC120093497 (49% identical), chimpanzee U4 (47% identical), dog U4 (47% identical), mouse Gm22249 (42% identical). Paralogues in human: RNU4-74P (48% identical), RNU4-72P (45% identical), RNU4-39P (44% identical), RNU4-48P (43% identical), RNU4-82P (43% identical), RNU4-18P (43% identical), RNU4-57P (41% identical), RNU4-64P (41% identical), RNU4-67P (41% identical), RNU4-5P (41% identical), RNU4-9P (41% identical), RNU4-13P (40% identical), and 81 more.